BRD10 (bromodomain containing 10)
Synonyms: KIAA2026; FLJ20375
Tractability: PROTAC: ubiquitination databases record sites on it.
Gene: Protein-coding gene on chromosome 9 (5,881,596 to 6,008,482, reverse strand). Ensembl gene ENSG00000183354.
Subcellular location: Nucleus
Subcellular location (Human Protein Atlas): Cytosol; Vesicles; Nucleoplasm
Gene Ontology:
Cellular component: nucleus
Genetic constraint (gnomAD): Loss-of-function variants: 63 observed, 138.15 expected, observed/expected ratio (o/e) 0.46, 90% interval 0.37 to 0.56. The synonymous counts are far from expectation, so gnomAD's model fits this gene poorly and the ratio says little. Missense variants: 3,124 observed, 2,463.7 expected, observed/expected ratio (o/e) 1.27, 90% interval 1.23 to 1.31. Synonymous variants: 1,178 observed, 911.41 expected, observed/expected ratio (o/e) 1.29, 90% interval 1.23 to 1.36.
Homologues: Orthologues: chimpanzee BRD10 (99% identical), macaque BRD10 (96% identical), pig BRD10 (87% identical), dog BRD10 (87% identical), rabbit BRD10 (85% identical), rat Brd10 (78% identical), mouse Brd10 (77% identical), guinea pig BRD10 (76% identical), tropical clawed frog BRD10 (40% identical).
Diseases named in the same sentence as BRD10 in open-access papers:
BRD10 is named in the same sentence as 1 disease in open-access papers, as found by Europe PMC text mining. Sharing a sentence is not in itself a finding about the gene and the disease.
BRD10 shares sentences with these, for which no sentence is quoted: asthma (1 paper).